CXCR5 (C-X-C motif chemokine receptor 5)
Diseases named in the same sentence as CXCR5 in open-access papers (continued):
Sharing a sentence is not in itself a finding about the gene and the disease.
gastric cancer (13 papers, 2015 to 2025). A primary or metastatic malignant neoplasm involving the stomach. "Studies that examined an association between CD8+T and prognosis in gastric cancer are inconsistent, and a distinct population of CXCR5+CD8+T associated with better overall survival has been reported among various malignancies." (PMID 34035252, 2021). "Here, we show that the abundance of intratumoral CXCR5+CD8+T cells is associated with better overall survival in patients with gastric cancer." (PMID 34035252, 2021). "Patients with gastric cancer who exhibited high infiltration of CXCR5+CD8+ T cells had longer OS than those with lower infiltration of CD8+ T cells." (PMID 39840050, 2024). "Research has shown that CD40 can regulate the expression of CXCR5 in MDSCs, influencing their recruitment and accumulation in gastric cancer." (PMID 39840050, 2024). "In the field of GI cancer, a promalignant role of the CXCL13/CXCR5 axis has been shown for pancreatic cancer and gastric cancer as well as hepatocellular carcinoma." (PMID 36077611, 2022). "Patients with TNM II + III gastric cancer with higher intratumoral CXCR5+CD8+T cell infiltration are more likely to benefit from adjuvant chemotherapy." (PMID 34035252, 2021). "Identification of the clinical significance and phenotype of gastric cancer infiltrating CXCR5+CD8+T provides a roadmap for patient stratification and trials of targeted therapies." (PMID 34035252, 2021). "For example, expression levels of CXCR3, CXCR4, and CXCR5 displayed a marked increase in gastric cancer and were significantly correlated to the prognosis of patients." (PMID 34337085, 2021). "Here the authors show a consistent association between higher density of intratumoral CXCR5+CD8+ T cells and longer overall survival in four different cohorts of patients with gastric cancer." (PMID 34035252, 2021). "Gastric cancer infiltrating CXCR5+CD8+T cells represent a specific subtype of stem-like CD8+T with effector memory feature." (PMID 34035252, 2021). "Our results indicate that CD40 regulates the recruitment and accumulation of MDSC in gastric cancer by controlling CXCR5 expression in MDSC." (PMID 26462153, 2015). "Also, CXCL13 and CXCR5 are implicated in tumor growth and metastasis, with CXCL13 serving as a predictive marker for chemotherapy response in advanced gastric cancer patients." (PMID 40445003, 2025). "Additionally, a study of cellular content in gastric cancer tissue showed that CXCR5+CD8+ T cells are predominantly present in both gastric cancer and paracancerous tissues." (PMID 39840050, 2024). "PPI network analysis highlighted eight key hub genes (CD80, CCR9, CXCR3, CXCR5, CXCR6, CCR3, CCL20, and CXCL1), revealing their pivotal roles in gastric cancer and H. pylori infection." (PMID 40445003, 2025). "A further analysis of the CXCR5+CD8+ T signature, which has been proposed as a possible biomarker of immunotherapy response in gastric cancer, showed high expression in IIH-FH tumours, while tumours belonging to the IIL-FL presented reduced expression." (PMID 36253523, 2022). "Hence, we sought to investigate the involvement of CXCR5+CD4+ Tfh cells and CD19+CD24hiCD38hi Breg cells in gastric cancer." (PMID 36339942, 2022).
colon carcinoma (12 papers, 2008 to 2024). "CXCL13 and CXCR5 are associated with poor prognosis in advanced colon cancer." (PMID 33579281, 2021). "PD-1, TIM3, 2B4, and Lag3 are downregulated in CXCR5+CD8 T cells in colon cancer, but within gastric cancer PD-1, Lag3, CTLA4, and Tigit are upregulated." (PMID 36314014, 2022). "According to research, the CXCL13/CXCR5 axis promotes colon cancer incidence, progression, and metastasis by secreting MMP13 and activating the PI3K/AKT pathway." (PMID 34922542, 2021). "The PI3K/AKT pathway also plays a key role in the CXCL13/CXCR5 axis, promoting colon cancer growth and invasion." (PMID 34947813, 2021). "Among the CXC chemokines, CXCL13, and its receptor, CXCR5, have been reported to be involved in the development of breast cancer, colon cancer, and lymphoma." (PMID 30723697, 2018). "In one report, immunohistochemistry revealed CXCR5 expression in a significant proportion of human colon carcinoma specimens, whereas another group demonstrated cytoplasmatic expression in pancreatic cancer cells and cell lines." (PMID 18781150, 2008). "In colorectal or colon cancer, the CXCL13/CXCR5 axis mediates the pathogenesis, development, and distal metastasis of tumor cells through upregulating the expression and secretion of MMP13, as well as activating the PI3K/Akt pathway." (PMID 34947813, 2021). "Flow cytometric analysis of surface protein expression on CT-26 cells demonstrated clear-cut expression of CXCR2, CXCR3, CXCR4 and CXCR5, suggesting a potential role of CXC chemokines in colon cancer cell biology." (PMID 34115261, 2021). "CXCR5 promotes proliferation of clear cell renal carcinoma through activating PI3K/AKT/mTOR pathway in the presence of its ligand, CXCL13, and this signaling pathway has also been reported in colon cancer proliferation." (PMID 36314014, 2022). "The CXCL13/CXCR5 axis promotes tumor progression through the PI3K/AKT/mTOR pathway, contributes to poor prognosis in clear cell renal cell carcinoma, and promotes the growth and invasion of colon cancer cells via the PI3K/AKT pathway." (PMID 33213490, 2020).
colorectal cancer (12 papers, 2015 to 2023). A primary or metastatic malignant neoplasm that affects the colon or rectum. "CXCR5 is the receptor of C-X-C motif chemokine ligand 13 (CXCL13); CXCL13/CXCR5 signaling axis activity can accelerate the progression of colorectal carcinoma by activating the PI3K/AKT pathway." (PMID 38049474, 2023). "A further study showed that polarized M2 macrophages mediate premetastatic niche formation and facilitate colorectal cancer liver metastasis by forming a positive-feedback loop of CXCL13/CXCR5/NFκB/p65/miR-934." (PMID 34947813, 2021). "Further, CXCR5+ CD8 T cells in colorectal cancer maintain a cytolytic capacity to directly lyse tumor cells but can also influence B cell secretion of IgG, suggesting multiple mechanisms for tumor control by these cells." (PMID 31275308, 2019). "As pancreatic and colorectal cancer disease-free survival time is positively correlated with CXCR5+ CD8 T cell frequency, the maintenance of a CXCR5+ CD8 T cell population may prolong cancer treatment efficacy." (PMID 31275308, 2019). "A role for intestinal CXCR5+ Th cells in sustaining cell-mediated immunity and inflammation, most likely through secretion of IL-21, has been supported by experimental animal models as well as in expression analyses of material from patients with colorectal cancer and inflammatory bowel disease." (PMID 35355990, 2022). "The frequency of CXCR5+ CD8 T cells isolated from pancreatic and colorectal cancer tumor masses correlate with improved patient outcomes suggestive of tumor control." (PMID 31275308, 2019). "We focused on the CD8+CXCR5+ T cell population in HCC patients because this cell subtype, especially in the tumor microenvironment, has not been investigated in HCC and was found to possess high functionality in colorectal cancer and LCMV infection." (PMID 31663864, 2019).
diabetes (12 papers, 2015 to 2024). "Many subsets of Tfh cells, such as CXCR5+ PD1+ ICOS+ and CD4+ CXCR5+ PD-1+, are increased in children and adults with diabetes." (PMID 36776877, 2023). "Research studies showed that ICOS ligand enhanced the homing of Tfh to the follicular region through the induction of C-X-C motif chemokine receptor 5 (CXCR5) as well as the chemotaxis of Treg to pancreas islet through CXCR3 in in early phase of diabetes." (PMID 37325657, 2023). "Recent work further identified that CXCL13/CXCR5 contributes to diabetes-induced mechanical hypersensitivities by activating pERK, pSTAT3, and pAKT pathways and promoting TNF-α and IL-6 production in SCDH." (PMID 33602238, 2021). "In conclusion, SNO-GNAI2 drives diabetes-accelerated atherosclerosis by coupling with CXCR5 and activating YAP-dependent endothelial inflammation, and reducing SNO-GNAI2 is an efficient strategy for alleviating diabetes-accelerated atherosclerosis." (PMID 34294713, 2021). "Notably, we found that SNO-GNAI2 inactivated Hippo-YAP signaling through coupling to CXCR5, which contributed to endothelial inflammation during diabetes-accelerated atherosclerosis." (PMID 34294713, 2021). "Similarly, a recent study showed that CXCL13 activates ERK in the spinal cord through CXCR5 in a mouse model of diabetes-induced tactile allodynia." (PMID 33161894, 2020). "Interestingly, transfer of T cells with a Tfh cell phenotype (obtained from pooled pancreatic lymph nodes from diabetic mice and enriched according to CXCR5 expression) transferred diabetes to recipient animals more efficiently than CXCR5-depleted T cells." (PMID 30065726, 2018). "Here the authors show that the coupling efficiency of GNAI2 with CXCR5 is enhanced by S-nitrosylation of GNAI2, leading to Hippo-YAP dysfunction in endothelium, and plays a role in diabetes-accelerated atherosclerosis." (PMID 34294713, 2021). "Follicular helper T-cells (Tfh) of diabetic patients express elevated levels of C-X-C motif chemokine receptor 5 (CXCR5), and there is a dysregulation of circulating CD4+ CXCR5 + T-cells in diabetes patients." (PMID 34516309, 2021). "Specifically, they transferred ovalbumin-specific CXCR5+ or CXCR5−CD4+ T cells into recipient mice expressing ovalbumin under the insulin promoter in the β-cells and observed a significant increase in diabetes incidence in mice receiving CXCR5+CD4+ T cells." (PMID 30083169, 2018). "Thus, it is reasonable to conclude that the increase of PD-1+CXCR5+CD4+ Tfh cells in peripheral blood from DR patients could reflect GCs dysregulation and aberrant immune responses in the lymphoid and non-lymphoid tissues during diabetes." (PMID 32226551, 2020).
melanoma (12 papers, 2020 to 2026). A malignant, usually aggressive tumor composed of atypical, neoplastic melanocytes. "Metacluster C58748 represented CD4+CD45RO+ T cells that expressed CCR6, CCR7, CXCR3 and CXCR5 suggesting TFH cells in melanoma which exhibit elevated CEACAM1 levels in the context of treatment-resistant compared to treatment-naive disease." (PMID 38956268, 2024). "Moreover, there were increased proportions of metastatic patients with higher expression of CXCR5 and PRDM1 in Treg cells, suggesting that high levels of CXCR5 and PRDM1 in Treg cells are correlated with increased risk of melanoma metastasis." (PMID 34798898, 2021). "The CXCL13/CXCR5-axis, with its prominent role in launching adaptive immune responses and its circulating soluble and cellular components, could be an additional promising resource for anti-cancer biomarker research in immunogenic tumors, such as melanoma." (PMID 36836910, 2023). "TLS co-infiltrating CD8+ T cells and CD20+ B cells enhanced survival in metastatic melanomas co-expressing CXCR5 and CXCL13, whereas B-cell-enriched melanomas were accompanied by increased levels of naive or memory T cells." (PMID 35563678, 2022). "Consistent with the increased proportions of metastatic melanoma patients expressing high levels of FOXP3, PRDM1 and CXCR5, we have detected TFR cells in melanoma across the different metastatic tissues." (PMID 34798898, 2021). "The overall survival rate of patients with high expressions of CCR7, CXCR5, EOMES, GBP4, TNFRSF9 and STAT1 in melanoma was significantly higher, which is consistent with the significantly higher survival rate observed for the young cohort receiving immunotherapy." (PMID 36135194, 2022). "Treg signature genes CXCR5, TNFRSF9, CCR7, STAT1, GBP4, and EOMES were significantly upregulated in the young cohort and were correlated with higher survival in melanoma, while ID3, IL-17A, IL-17F, RDH10 and IL-11 were significantly upregulated in the old cohort." (PMID 36135194, 2022). "However, in the analyzed mouse and human melanoma RNAseq datasets CXCR5 was not enriched in Tpes, neither allowed identification of Tcf1+ cells by flow cytometry in B16.OVA tumors." (PMID 32174925, 2020). "Although CXCR5 is not included in all analyses, the identified subsets display increased T‐cell functionality within tumor infiltrating lymphocytes, and PD‐1+Tcf1+ CD8 T cells are positively correlated with survival and clinical response to PD‐1 ICB in melanoma." (PMID 33098668, 2021).
B cell lymphomas (11 papers, 2010 to 2023). "CXCL13 is the agonist of Tfh defining marker CXCR5, and its serum levels have been proven to predict B-cell NHL risk in HIV+ individuals." (PMID 37297008, 2023). "As known, tumor-promoting functions and malignant B cells rescue of Tfh cells were discovered in hematological malignancies, and CXCR5 CAR-T cells targeting Tfh cells improved the therapeutic effect of immunotherapy in B cell non-Hodgkin's lymphoma (B-NHLs)." (PMID 36339942, 2022). "Currently, we are evaluating the potential advantage of CXCR5/CD19 CAR-T over the classical CD19 CAR-T in treating B cell lymphomas." (PMID 34553036, 2021). "CXCL13, the ligand for CXCR5, is overexpressed in salivary glands of pSS patients, and increased expression of CXCL13 is associated with increased B cell hyperactivity, and development of B cell lymphoma." (PMID 36505431, 2022). "Among these genes, we found five genes, ATP5L, BCL9L, CD3G, CXCR5, and DDX6, that have been reported to be associated with the occurrence of B-cell lymphomas, a blood cancer caused by the disorder of immune functional B cells (also known as B lymphocytes) that attack invading pathogens." (PMID 36173765, 2022). "To target both B cell Non-Hodgkin’s lymphoma (B-NHLs) and follicular T helper (Tfh) cells in the tumor microenvironment (TME), we apply here a chimeric antigen receptor (CAR) that recognizes human CXCR5 with high avidity." (PMID 33431832, 2021). "It should be noted that CXCR5 and/or CXCL13 have been shown to be associated with several non-AIDS-related B cell lymphomas, including extragastric lymphoma of mucosa-associated lymphoid tissue (MALT) and follicular lymphoma." (PMID 21490903, 2010). "CXCL13 and its receptor, CXCR5, are required for B-cell homing to follicles in lymph nodes, suggesting that aberrant CXCL13 expression may be involved in the pathogenesis of B-cell lymphoma through abnormal chemotaxis of B-cells to tissues or abnormal B-cell activation." (PMID 30873511, 2018). "Thus, further study of CXCR5 and CXCL13 expression and function in AIDS-NHL, and in non-AIDS-associated NHL, could ultimately reveal some unique differences between the pathogenesis of AIDS-related and non-AIDS-related B cell lymphomas." (PMID 21490903, 2010).
colitis (11 papers, 2020 to 2025). Inflammation of the colon. "We observed higher expression of Cxcr5 in mesenteric lymphatic B cells and higher expression of Cxcl13 in the intestine of colitis mice." (PMID 38785804, 2024). "We determined the frequencies of Tregs (CD4+FOXP3+), Th1 cells (CD4+CXCR3+), and Tfh cells (CD4+CXCR5+) in the colonic lamina propria in DSS-induced colitis." (PMID 38396052, 2024). "Additionally, the mRNA expression level of Cxcr5 was significantly elevated in MLB cells derived from DSS-induced colitis rats." (PMID 38785804, 2024). "Similarly, colitis rats receiving feed with low-molar-mass oat beta-glucan (βGl+) upregulated the expression of only four genes (Ccl19, Cxcl10, Cx3cr1, Cxcr5) in this stage of colitis." (PMID 35163326, 2022). "The deficiency of CXCL13 can effectively alleviate the occurrence and the development of DSS-induced colitis by limiting CD4+CXCR5+ T cells migration from mesenteric lymph nodes to secondary lymphoid organs, and thereby inducing local regulatory B cells increase in colon." (PMID 36172372, 2022). "In this study, we evaluated whether cell percentages of CD4+CD45RA+CCR7+CXCR5+ (CD4+ mTfh) cells changed in experimental colitis." (PMID 35388299, 2022). "Compared with the normal group, the numbers of CD4+CXCR5+BCL-6+, CD4+CXCR5+ICOS+, CD4+CXCR5+PD-1+, and CD4+CXCR5+PD-L1+ T cells were significantly elevated, while CD4+CXCR5+Blimp-1+ T cells were inhibited in the peripheral blood of colitis mice in the DSS group." (PMID 32581849, 2020). "RNA sequencing revealed increased Cxcr5 expression in MLB cells from colitis rats, while real-time PCR indicated an upregulation of its ligand Cxcl13 in the colon of colitis rats." (PMID 38785804, 2024). "On day 11 of DSS-induced colitis, spleen and mesenteric lymph nodes (MLN) of mice were taken to detect the percentage of CD4+CXCR5+ T cells and regulatory CD5+B cells by flow cytometry." (PMID 36172372, 2022). "In conclusion, our study demonstrated a elevation of CXCL13 in both IBD patients and DSS-induced colitis mice, which contributed to the recruitment of CD4+CXCR5+ T cells to secondary lymphoid organs, thereby promoting the production of regulatory CD5+ B cells." (PMID 36172372, 2022). "Although the present study did not detect alterations in CXCL13 and CXCR5 expression in MLB cells from TNBS-induced colitis rats, we observed upregulated mRNA expression of Ccr8, a receptor for the T cell-derived chemokine Ccl1, in these rats." (PMID 40331987, 2025). "To ascertain whether CXCR5 plays a crucial role in MLB cells migration to the colon, we compared the mRNA expression of Cxcl13 (the specific ligand of Cxcr5) in colonic tissues of NC and DSS-induced colitis rats through real-time PCR." (PMID 38785804, 2024). "In contrast with mice in the DSS group, the numbers of CD4+CXCR5+ BCL-6+, CD4+CXCR5+ICOS+, and CD4+CXCR5+PD-1+ T cells were decreased, and CD4+CXCR5+Blimp-1+ T cells were significantly increased after colitis was treated with SSP and 5-ASA for 7 days." (PMID 32581849, 2020). "After 7-days’ administration of SSP and 5-ASA, the numbers of CD4+CXCR5+IL-10+ (Tfh10) and CD4+CXCR5+Foxp3+ (Tfr) (E5) were dramatically increased when compared with those in colitis mice without treatment." (PMID 32581849, 2020). "The results showed that percentages of CD4+CXCR5+PD-1+ Tfh and Tfh/Tfr ratios in the MLNs and spleen of colitis mice increased significantly compared to those of normal mice (p < 0.05), while no statistical difference was found in CD4+CXCR5+Foxp3+ Tfr (p > 0.05)." (PMID 34707499, 2021).